IL17A (interleukin 17A)
Diseases named in the same sentence as IL17A in open-access papers (continued):
Sharing a sentence is not in itself a finding about the gene and the disease.
psoriasis (continued). "The present study showed that the combination of AuNPs with specific anti‐IL17A Apt (M2) in an IMQ‐induced psoriasis mouse model boosted the anti‐inflammatory effect of anti‐IL17A Apt, especially in low dose, and alleviated the symptoms of psoriasis in the back skin of C57BL/6 mice." (PMID 41477217, 2025). "Secukinumab, an FDA- and EC-approved psoriasis biologic targeting IL-17A, is also in AD studies." (PMID 40309262, 2025). "In contrast, in vivo models, such as imiquimod (IMQ)-induced psoriasis in mice, demonstrate that IL-17A signaling ablation significantly reduces skin inflammation, allowing direct assessment of disease phenotypes and therapeutic efficacy (e.g., FXYD3 deletion mitigates severity)." (PMID 40948748, 2025). "In mice with overexpressed IL-36α in keratinocytes but an otherwise normal phenotype, 12-O-tetradecanoylphorbol-13-acetate (TPA) treatment results in a considerable increase in skin inflammation that morphologically mimics psoriasis, as well as a significant rise in IL-17A, IL-22, and IL-23." (PMID 40563994, 2025). "Moreover, IL-17A, the key pathophysiological driver of psoriasis, also contributes to the pathological process of AIS." (PMID 40584532, 2025). "Additionally, γδ T cells contribute to psoriasis by secreting pro-inflammatory cytokines such as IL-17A, IL-17F, and IL-22, promoting inflammation and keratinocytes proliferation." (PMID 40406126, 2025). "This case demonstrates xeligekimab—a novel fully humanized anti-IL-17A IgG4 monoclonal antibody (China-approved, August 2024)—effectively managing concurrent psoriasis, hidradenitis suppurativa, hepatitis B, and metastatic colorectal cancer, providing clinical validation for this paradigm shift." (PMID 41142781, 2025). "This was the main objective of the present study, in which we have performed a pharmacogenomic genome-wide association study (GWAS) of treatment response to all the inhibitors of the IL-17A, signaling in a cohort of 88 Greek patients with moderate to severe psoriasis." (PMID 41153404, 2025). "Furthermore, IL-17A appears to be one of the most prominent cytokines involved in the pathogenesis of psoriasis." (PMID 38540199, 2024). "Recently, IL-17A-specific antibodies were developed for the treatment of psoriasis." (PMID 39584990, 2024). "In addition, the 3D TNFF‐α, IL17A and IL22 skin models clearly demonstrated the roles of TNF‐α, IL‐17A and IL‐22 in the formation of the epidermal structure and expression of psoriasis‐related molecules." (PMID 39624730, 2024). "Dual blockage of TNF-α and IL-17A repressed the inflammatory psoriasis phenotype." (PMID 39558145, 2024). "Therefore, it appears that changes in the gene expression of Kynu, Camp, Defb2, and Penk are more appropriate candidates for the analysis of IMQ-induced psoriasis and anti-IL-17A aptamer treatment in this model." (PMID 39045230, 2024). "Additionally, bimekizumab, which targets both IL-17A and IL-17F, is currently approved for psoriasis treatment." (PMID 39684717, 2024). "The presence of IFN-γ and TNF-α may augment the potential effects of IL-17A on the pathogenesis of psoriasis and atherosclerosis." (PMID 39104857, 2024). "Therapeutic antibodies for blocking IL-17A have been developed for psoriasis and ankylosing spondylitis and one trial was registered combining secukinumab (anti-IL17) with camrelizumab (anti-PD1) therapy, but the current trial status is still unknown." (PMID 39080202, 2024). "In addition to Th17 cells, neutrophils represent a category of cells that can contribute to IL-17A production and the perpetuation of psoriasis development." (PMID 38793117, 2024). "Topical application of the selective ARβ1 agonist dobutamine hydrochloride (DOB) to IMQ‐treated mice aggravated psoriasis‐like manifestations and promoted γδT‐cell IL‐17A production in skin; application of the selective ARβ1 antagonist acebutolol hydrochloride (ACE) had the opposite effects." (PMID 38544478, 2024).
psoriasis (continued). "And studies have shown that CXCL8 could recruit neutrophils and CCL20 chemotactically attracts IL-17A-producing immune cells, further creating an IL-17A-rich environment and accelerating the pathological progression of psoriasis." (PMID 38803495, 2024). "Additionally, cis-Khellactone, an inhibitor of pro-inflammatory macrophages, promotes autophagy, reduces the infiltration of dermal macrophages in psoriasis, and markedly inhibits the production of IL-17A by Th17 cells." (PMID 38606161, 2024). "IL-17A, IL-17F, and IL-22 are elevated in the sera and/or skin lesions of patients with psoriasis." (PMID 39114670, 2024). "Moreover, IL-17A inhibitors suppress disease activity in psoriasis, PsA and AS, supporting the evidence of IL-17A contributing to the disease pathogenesis." (PMID 38292069, 2024). "Second, the study performed targeted metabolic analysis of LCFA alterations in psoriasis patients receiving pretherapy and posttreatment with anti-IL-17A mAb, which was a unique approach compared to previous metabolic analyses comparing healthy volunteers and psoriasis patients." (PMID 38185620, 2024). "It has been discovered that IL-17A expression increases 5 times from mild to severe psoriasis." (PMID 38827737, 2024). "In addition to this, in the emerging field of the innate immune system, innate lymphoid cells (ILC) 3 in ILC appear to be important in psoriasis because of their ability to produce IL-22 and IL-17A." (PMID 39720727, 2024). "Moreover, circulating exosomal IL-17A level was significantly higher in patients with moderate-to-severe psoriasis compared with those with mild psoriasis." (PMID 38481799, 2024). "Accordingly, a newly constructed protein degrader for IL-17A was found to be effective in ameliorating imiquimod-induced psoriasis, suggesting that macrophages could be responsible for this assembled IL-17A degradation." (PMID 38791342, 2024). "Anti-IL-17A secukinumab and anti-IL-23 guselkumab have yielded disappointing results in the treatment of pustular psoriasis, achieving only Palmoplantar Psoriasis Area and Severity Index 75 in 26.6% and 11.5–20.4% of patients at week 16, respectively." (PMID 38448036, 2024). "The inflammatory reactions in psoriasis are dependent on the IL-23/IL-17A inflammatory axis." (PMID 39273201, 2024). "Baseline substudy serum samples from patients with psoriasis (n = 118) contained significantly (all P < .01) higher concentrations of IL-17A, IL-17F, IL-22, IL-8, CCL22/macrophage-derived chemokine (MDC), and CCL4/MIP-1β than an independent, healthy control serum cohort (n = 25)." (PMID 39114670, 2024). "Epidermal infiltration of neutrophils, a histopathological marker of psoriasis, with consequent activation, leads to the formation of neutrophil extracellular traps (NETs), which further interact directly with keratinocytes and heighten the IL-17A response." (PMID 38255729, 2024). "Considering the potential influence of body mass index (BMI) on the quantitative results of LCFAs in serum samples among psoriasis patients, although healthy volunteers and psoriasis patients had similar BMIs, a significant increase in BMI was observed after anti-IL-17A mAb treatment." (PMID 38185620, 2024). "This study evaluates neutrophil-to-lymphocyte ratio (NLR) and platelet-to-lymphocyte ratio (PLR) in psoriasis patients and five murine models of psoriasis-like skin disease based on topical imiquimod application and overexpression of IL-17A under different promotors." (PMID 38127137, 2024). "IL-6 and IL-22 work synergistically with IL-17A as potent STAT3 activators in psoriasis." (PMID 38892253, 2024). "We found that in the skin of psoriasis-like mice, Il1b and Il6 were mainly expressed in neutrophils, while Il17a was mainly expressed in T cells, Il18 was mainly expressed in macrophages and fibroblasts, and Tnfa was mainly expressed in macrophages and T cells." (PMID 39717896, 2024).
psoriasis (continued). "In addition, Th17 cells are a new type of Th cells that actively participate in inflammatory responses and secrete the key pro-inflammatory cytokine IL-17A, which has been found to be up-regulated in psoriasis lesions and synovial fluid." (PMID 38255845, 2024). "It is thus hypothesized that younger psoriasis patients may have lower IL‐17A, IL‐17A/F, or IL‐17F‐mediated immune responses, which may be more susceptible to bimekizumab treatment compared to elderly patients." (PMID 38482898, 2024). "Moreover, the blockade of IL-17A with monoclonal antibodies (anti-IL-17A) in psoriasis, PsA, and AS has proven to be a highly effective therapeutic approach." (PMID 38292069, 2024). "Targeted intervention of psoriasis by neutralization of IL‐17A may provide a candidate therapeutic measure for its depression comorbidity." (PMID 39660880, 2024). "Pathway enrichment analysis of the DEG identified a significant over-representation of IL-17 related genes (“Role of IL-17A in psoriasis”; FDR < 10−4 in supra-spinous keratinocytes, FDR < 10−2 in spinous keratinocytes), confirming the suppressive effect of IL-23 inhibition on T17 activation." (PMID 38291032, 2024). "However, JAK inhibitors are also effective in treating psoriasis, potentially due to their ability to interrupt the skin inflammation-mediated inflammatory cycle and reduce the overproduction of IL-17A." (PMID 39519167, 2024). "Additionally, IL-17RA interacts with and transactivates the epidermal growth factor (EGFR), which mediates a complex IL-17A-induced signaling network in psoriasis." (PMID 38892253, 2024). "However, IL17A blockade is very effective only for psoriasis, psoriatic arthritis, and axial SpA, and several monoclonal antibodies that selectively target this cytokine have now been approved and marketed." (PMID 38672170, 2024). "Consequently, there is a growing interest in exploring the expression of inflammatory mediators like IL-17A in the context of the relationship between EVs and psoriasis." (PMID 39771564, 2024). "In psoriasis patients, IL-17A may synergize with other inflammatory cytokines like TNF-α and IFN-γ, enhancing its effects on atherosclerosis." (PMID 39104857, 2024). "Furthermore, abnormal LCFAs metabolism is improved in psoriasis patients atfer receiving therapy of anti-IL-17A mAb." (PMID 38185620, 2024). "γδ T cells mainly secrete IL17A to promote the pathogenesis of psoriasis." (PMID 38566145, 2024). "IL-17A inhibitors restore microbiota homeostasis and metabolic pathways, reduce pro-inflammatory cytokine expression, and alleviate symptoms in patients with Psoriasis." (PMID 38482003, 2024). "Psoriasis is a chronic inflammatory skin disease, and its pathogenesis may be related to the overproduction of interleukin-17A (IL-17A)." (PMID 38185620, 2024). "Since IL-17A is a crucial mediator in the pathogenesis of psoriasis, inducing the proliferation and secretion of inflammatory mediators by KCs, we next investigated whether IL-17A could modulate AIM2 expression in KCs." (PMID 39352743, 2024). "Interestingly, we found that the most significant canonical pathway is IL17A in Psoriasis [pvalue: 2.65E-08, -log (p-value: 7.58)] amongst 16 canonical pathways identified by IPA with a p-value of ≤ 0.05." (PMID 39911581, 2024). "Taking into account that macrophage and LC-derived IL-23 activates Th17 lymphocyte differentiation as well as IL-17A production by γδ T cells, one can conclude that M1-polarized dermal macrophages and LCs are the central cells that drive psoriasis-related autoimmune reaction." (PMID 38791342, 2024). "Moreover, dermal endothelial cells are activated by psoriasis cytokines, including IL-36γ and IL-17A, which induce their proliferation, secretion of proinflammatory cytokines and chemokines, and upregulate ICAM-1 expression." (PMID 38642273, 2024).
psoriasis (continued). "Additionally, a retrospective study reported significant increases in BMI and weight in patients with psoriasis after 24 weeks of anti-IL-17A mAb treatment." (PMID 38185620, 2024). "One of the important cytokines with a main role in the development of psoriasis is IL-17A." (PMID 39045230, 2024). "Anti-inflammatory action in psoriasis through inhibition of IL-17A production." (PMID 39203553, 2024). "Given the therapeutic roles of IL-17A in psoriasis and the pathological features of macrophage infiltration around the epidermal-dermal interface in psoriasis patients, we conducted in vivo experiments to evaluate the efficacy of our IL-17A-clearing LYTACAs for treating psoriasis." (PMID 38396109, 2024). "In IMQ‐treated mice, subcutaneous NE injection aggravated psoriasis‐like manifestations, eliminated the difference in skin thickness between WT and Camk2gfl/flDat‐Cre mice, increased the number of IL‐17A+ γδT cells in skin and rescued the Camk2g deletion–induced reduction of this number." (PMID 38544478, 2024). "The 2020 research indicates that there is enhanced acetylation of H3K9 and H3K27 in the IL17A promoter region in the immune cells of psoriasis patients, which induced differentiation of Th17 and γδ T17 cells (which produce IL-17A γδ T cells), resulting in immune imbalance and disease progression." (PMID 38612637, 2024). "Key cytokines involved in the pathogenesis of psoriasis, including IL-17A, IL-17C, IL-17F, and IL-22, may contribute to this phenomenon." (PMID 39126010, 2024). "Notably, arachidonic acid and eicosanoic acid had AUC values close to 1.0 in both the PSV/HC comparison and W8/PSV comparison, indicating that they can be used as predictive markers to evaluate the efficacy of anti-IL-17A mAb therapy in psoriasis patients." (PMID 38185620, 2024). "Modern research indicates that psoriasis and atherosclerosis may share similar immune pathways related to the IL-17A axis." (PMID 39104857, 2024). "Consequently, our findings regarding the substantial inhibitory effects of montelukast on IL-17A and Th17 cells in mouse models of psoriasis emphasized its considerable potential as a therapeutic intervention for psoriasis." (PMID 38617532, 2024). "In IMQ-induced psoriasis models, IL17A was mainly secreted by Rorc-tdTomato-positive γδ T cells." (PMID 38566145, 2024). "In addition, there was also a positive correlation between every two detected indexes among HMGB1, TLR4, IL‐23, and IL‐17A in psoriasis patients." (PMID 38414294, 2024). "These cytokines collectively induce keratinocyte proliferation, differentiation, and inflammatory activation, with IL-17A serving as the principal effector cytokine driving psoriasis pathogenesis and being essential for the development and maintenance of psoriatic plaques." (PMID 39126010, 2024). "Psoriasis-like erythematous appearance and microscopic features were significantly reduced, along with a notable decrease in the tissue gene expression of core psoriasis cytokines, such as IL-23, IL-17A, IL-22, TNF-α, and IL-6, after the capsaicin treatment." (PMID 39338338, 2024). "This correlation was corroborated in five murine models of psoriasis-like skin disease based on topical imiquimod application and IL-17A overexpression under different promotors, in which the elevation of NLR — but not PLR — appeared to reflect severity and early-onset of psoriatic inflammation." (PMID 38127137, 2024). "Consequently, weighing these potential complications when considering anti-IL-17A/IL-17RA biologics is imperative, especially in psoriasis patients with pre-existing bacterial infections or inflammatory bowel disease." (PMID 39684717, 2024). "Moreover, IL-1R1 blockade significantly reduced the population of IL-17 A-producing γδ T cells, CD4+ T cells, and CD8+ T cells, consistent with the role of IL-1β in the development of IL-17 A-producing T cells and psoriasis pathogenesis." (PMID 38704587, 2024).
psoriasis (continued). "Given this large body of evidence, it is tempting to assume that targeting IL-17A and IL-23 might confer a protective role against tumor development in patients with moderate to severe psoriasis." (PMID 39518685, 2024). "Psoriasis is considered to be mainly dominated by Th17 cells and its effective cytokine IL‐17A." (PMID 39660880, 2024). "Although further investigations are needed to fully clarify its exact immune‐inflammation mechanism, we may believe that blocking IL‐17A may be an exactly effective approach for the treatment of psoriasis and its psychological comorbidities." (PMID 39660880, 2024). "In May 2022, bimekizumab, a humanized monoclonal antibody that binds both IL‐17A and IL‐17F, was approved in Japan for the treatment of patients with moderate‐to‐severe psoriasis aged ≥15 years." (PMID 38482898, 2024). "Furthermore, KCs stimulated by a combination of psoriasis-associated cytokines (TNF-α, IL-1A, IL-17A, IL-22, and oncostatin M) activate autophagic flux, which leads to recurrent psoriasis inflammation and increased skin barrier damage." (PMID 38606161, 2024). "Moreover, an anti-IL-17 mAb, secukinumab, can be used to restore the cancer-promoting effects of IL-17a and treat psoriasis in clinical practice." (PMID 38740736, 2024). "While the Th17 cytokine IL-17A has been implicated in the pathogenesis of psoriasis, psoriatic skin displays elevated expressions of IL-17A and IL-17F, which stimulate immune and non-immune cells and incite tissue inflammation." (PMID 38879568, 2024). "Our present study provides evidences that systemic IL‐17A can provoke microglia activation and neuroinflammatory effects, inhibit hippocampal neurogenesis, and trigger depression symptoms in pathological conditions of psoriasis." (PMID 39660880, 2024). "Notably, IL-17A has demonstrated promising results in psoriasis, where it not only suppresses skin inflammation but also ameliorates amyloidosis in the spleen." (PMID 39519167, 2024). "Together, these cytokines induce keratinocyte proliferation, differentiation, and inflammatory activation, although IL-17A constitutes the main effector cytokine driving psoriasis pathogenesis and is essential for the development and maintenance of psoriasis plaques." (PMID 38256115, 2024). "In addition to this, IL-17A can also inhibit autophagy by activating the PI3K/Akt/mTOR pathway, which in turn promotes psoriasis-associated inflammation." (PMID 39559368, 2024). "In the present study, LCAA-PSF was found to effectively slow down the inflammatory cytokine secretion of IMQ-induced psoriasis, including the expression of IL-23, IL-17A, TNF-α, and IL-6 in the serum and the expression of IL-17, Ki67, CK5/6 and VEGF in the affected skin area." (PMID 39062965, 2024). "Whether the amelioration of depression in psoriasis patients by IL‐17A inhibitor treatment is only a concomitant psychological change for their skin clearance or a positive result for specific IL‐17A targeting intervention?" (PMID 39660880, 2024). "In an imiquimod-induced psoriasis model in mice, an EO prepared with the aerial parts of P. canariensis, topically applied, was claimed to attenuate psoriasis symptoms in a manner similar to that of mometasone and to decrease the IL-23 and IL-17A serum levels." (PMID 38539820, 2024). "Furthermore, in comparison with IMQ-induced psoriasis mice, the downregulation of IL17A in skin tissues after DNT administration was confirmed through real-time PCR." (PMID 38566145, 2024). "Moreover, ILC3s have also been demonstrated to elicit psoriasis-like symptoms in mice by secreting IL-17A, IL-17F, and IL-22." (PMID 38255845, 2024). "Genetic and biological factors unique to psoriasis could further amplify IL-17A’s impact on atherosclerosis." (PMID 39104857, 2024). "In addition to its role in psoriasis, most lines of evidence suggest a pathological role of IL-17A in neurodegenerative diseases that affect the CNS." (PMID 38098004, 2023).